RET (ret proto-oncogene)
Diseases named in the same sentence as RET in open-access papers (continued):
Sharing a sentence is not in itself a finding about the gene and the disease.
adenoma (13 papers, 2000 to 2025). A neoplasm arising from the epithelium. "It is unclear whether these represent rare coincidences or germline RET mutations do have at least a permissive role in the formation of these adenomas." (PMID 35743266, 2022). "RET is expressed in normal mucosa, and its expression is lost in adenomas and adenocarcinomas because of an aberrantly methylation of CpG islands within its promoter." (PMID 29665843, 2018). "The presence of RET/PTC1 in adenomas and benign tumors indicates that RET/PTC1 probably acts synergistically with other factors that lead to malignancy." (PMID 22363533, 2012). "In the FGF23-producing adenoma sample (FGF_7), a fusion transcript involving exon 20 of FN1 and exon 11 of RET genes was detected." (PMID 41373459, 2025). "Of the 109 patients, five patients had RET mutations (38, –, 41); two cases with acromegaly, two cases with prolactinoma, and one NFPA (one macroadenoma and one microadenoma, and in three cases the adenoma size is not available)." (PMID 25494863, 2015). "Adenohypophysis areas and reticulin staining in pituitary tissue showed that altering the RET/apoptosis pathway induces somatotroph hyperplasia and this is enough for GH/ IGF-1 excess and gigantism, but not for generating an adenoma within our study timeframe." (PMID 34588620, 2021).
hepatocellular carcinoma (13 papers, 2013 to 2026). A malignant tumor that arises from hepatocytes. "Lenvatinib, a VEGFR1-3, FGFR1-4, PDGFRα, c-Kit and RET inhibitor, is one of the six approved systemic therapies for hepatocellular carcinoma, the most common form of liver cancer." (PMID 33804681, 2021). "The exosomal circUHRF1 regulated the expression of RET by sponging hsa-miR-449c-5p to promote the progression of hepatocellular carcinoma." (PMID 34249673, 2021). "Using hepatocellular carcinoma (HCC) tissues from in HCC patients, the protein levels of GFRa3 and phosphorylated RET were examined by immunohistochemistry (IHC) with automated cell acquisition." (PMID 32573073, 2020). "Anti-VEGF treatment increases survival and is the standard-of-care for hepatocellular carcinoma (HCC), with sorafenib (VEGFR2, PDGFR, Raf1 inhibitor), lenvatinib (VEGFR, FGFR, c-Kit and RET inhibitor) and regorafenib (VEGFR2, Tie2 inhibitor) being common treatments." (PMID 33804681, 2021).
Von Hippel Lindau syndrome (13 papers, 2005 to 2024). "Some PGLs are directly associated with genetic syndromes with common mutations, including mutations involving the rearranged during transfection (RET), succinate dehydrogenase subunits (SDHx), von Hippel-Lindau (VHL) syndrome, etc.." (PMID 37287034, 2023). "Extra-adrenal pheochromocytomas can be associated with hereditary conditions such as multiple endocrine neoplasia (MEN) type 2, von Hippel-Lindau syndrome, or mutations in the SDHB, SDHD, or RET gene." (PMID 39867070, 2024).
lymphoma (12 papers, 2013 to 2024). A malignant (clonal) proliferation of B- lymphocytes or T- lymphocytes which involves the lymph nodes, bone marrow and/or extranodal sites. "The REarranged during Transfection (RET) proto-oncogene was identified in 1985 as a novel transforming gene in NIH3T3 cells upon transfection with DNA isolated from human lymphoma cells." (PMID 37835559, 2023). "RET’s transforming potential was first described in 1985 using NIH/3T3 mouse fibroblastic cell lines transfected with rearranged lymphoma DNA containing a RET coding sequence." (PMID 37627175, 2023). "In 1985, the RET rearrangement was seen for the first time when lymphoma DNA was transfected in NIH-3T3 cells." (PMID 32560187, 2020). "TRIM27 also translocates with the RET tyrosine kinase giving higher catalytic activity than RET alone in lymphoma, and resulting in increased cell proliferation and tumorigenesis." (PMID 31342168, 2019). "Rearranged during transfection (RET) is one such receptor tyrosine kinase first discovered in 1985 as a novel transforming gene in NIH3T3 cells upon transfection with DNA isolated from human lymphoma cells, resulting in their oncogenic transformation." (PMID 35957881, 2022). "The location of the RET gene was determined to be on chromosome 10q 11.2 in 1985, and the gene subsequently named RET (re-arranged during transfection) after it was found to be rearranged during transfection in 3T3 cell lines with DNA from lymphoma cells." (PMID 23455356, 2013). "The RET proto-oncogene, located on the long arm of chromosome 10 (10q11.2), was first identified in 1985 by transfection of NIH 3T3 cells with human lymphoma DNA." (PMID 30072953, 2018).
parathyroid tumors (12 papers, 2013 to 2025). "Parathyroid neoplasms can also be associated with multiple endocrine neoplasia (MEN) syndromes MEN1, MEN2A, and MEN4, caused by mutations in the genes MEN-1, RET, and CDKN1B, respectively." (PMID 36900197, 2023). "The molecular pathogenesis of parathyroid tumors has already been partly elucidated; Heppner and Carling have reported that inactivating somatic mutations of tumor suppressor genes multiple endocrine neoplasia type 1 (MEN1), RET, and HRPT2/CDC73 have been identified in parathyroid tumors." (PMID 35879975, 2022).
breast tumors (11 papers, 2011 to 2025). "Our analysis using mouse models offers new insights, suggesting that RET expression levels could be a biomarker of post-lactation-associated breast tumors." (PMID 35044452, 2022). "RET is overexpressed in ∼50% of breast tumors and has been suggested as an alternative therapeutic target, particularly in light of the recent advances in novel RET inhibitors." (PMID 35044452, 2022). "We have previously shown that high RET levels in primary breast tumor samples correlate with decreased overall survival." (PMID 35044452, 2022). "Analysis of clinical samples collected from patients with breast tumors also demonstrates the overexpression of RET in a significant portion of these specimens." (PMID 32993133, 2020). "Indeed, our data support the addition of RETi to CDK4/6i and/or endocrine therapy as a therapeutic strategy following resistance to combined CDK4/6i and endocrine therapy in ER+ breast tumors exhibiting RET overexpression." (PMID 39931212, 2024). "However, there is a discrepancy in the percentage of the breast tumors overexpressing RET between the data collected using immunohistochemical and mRNA-level assessment methods." (PMID 32993133, 2020). "Recent data have suggested that RET variants or amplification may also occur in ∼1% of breast tumors or metastases, while tumor-specific expression of GDNF and ARTN is relatively frequent and can promote autocrine activation of RET downstream signaling." (PMID 30666215, 2018). "Using GEPIA, RET and FN1 levels were found to be significantly higher in breast tumor tissues than in normal tissues." (PMID 36601474, 2022). "RET overexpression in the absence of gene amplification has been detected in 40–60% of breast tumors across multiple tumor subtypes." (PMID 36918928, 2023). "RET protein overexpression without gene amplification has been observed in 40–60% of breast tumors." (PMID 36918928, 2023).
glioma (11 papers, 2014 to 2025). A benign or malignant brain and spinal cord tumor that arises from glial cells (astrocytes, oligodendrocytes, ependymal cells). "Furthermore, the GDNF–GFRA/RET pathway has been implicated in glioma models and may contribute to resistance/initiation of aggressive phenotypes." (PMID 41517303, 2025). "Glioma-associated DEGs AKT2, CCL3, STAT2, VEGFC were up-regulated and HIF1A, KRAS, RET, TGFB2 were down-regulated specifically in the dogs." (PMID 29352201, 2018). "Glioma-associated DEGs CD244, IL21, RET, TGFA were up-regulated and AQP9, IGFBP2, EGFR, SOX9 were down-regulated specifically in the rat." (PMID 29352201, 2018). "Notably, a patient with an isocitrate dehydrogenase wild-type glioma harboring a RET amplification achieved a near-complete response to the RET inhibitor selpercatinib." (PMID 41244832, 2025). "Further investigation revealed that pralsetinib, a selective RET inhibitor, exhibited significant antitumor activity against TMZ-resistant glioma cells both in vitro and in vivo." (PMID 41244832, 2025). "Suggestive associations were found between young adult THCA and gene fusions involving RET (FDR = 0.102) or NTRK3 (FDR = 0.102), as well as between later-onset gliomas and EGFR fusions (FDR = 0.102)." (PMID 34788626, 2021). "Furthermore, high RET expression has been observed in glioma, and RET fusions, including CCDC6-RET, have also been detected." (PMID 41244832, 2025). "The RET inhibitor pralsetinib exhibited potent antitumor activity against TMZ-resistant glioma in vitro and in vivo, regardless of RET expression levels." (PMID 41244832, 2025). "Importantly, six of them, except for RET and MITF, are involved in the DNA damage repair (DDR) pathway, indicating the importance of genomic instability in glioma genesis." (PMID 34885201, 2021). "Our study also revealed new cancer types harbouring known fusions (for example, BRAF fusion in rectal adenocarcinoma, FGFR3 fusion in prostate adenocarcinoma, RET fusions in colon adenocarcinoma and invasive breast carcinoma, EGFR–SEPT14 in low-grade glioma, and so on)." (PMID 25204415, 2014).
parathyroid adenoma (11 papers, 2011 to 2024). "According to various studies, CDC73, MEN1, CCND1, and RET were shown to be parathyroid adenoma susceptible genes." (PMID 35879975, 2022). "The target-PPI included differentially methylated genes as well as parathyroid adenoma susceptible genes (CDC73, MEN1, CCND1, RET)." (PMID 35879975, 2022). "Mutations in the RET proto-oncogene, causing a number of different endocrine tumour syndromes, can be seen in MEN2A (associated with parathyroid adenomas)." (PMID 21747852, 2011). "Moreover, while somatic CDC73 gene mutations have been reported in small subsets of sporadic parathyroid adenomas, no reports on somatic RET gene mutations in parathyroid adenoma have been noted." (PMID 33269427, 2021).
cholangiocarcinoma (10 papers, 2018 to 2025). A carcinoma that arises from the intrahepatic biliary tree (intrahepatic cholangiocarcinoma) or from the junction, or adjacent to the junction, of the right and left hepatic ducts (hilar cholangiocarcinoma). "The only available clinical trial data on RET targeting agents in cholangiocarcinoma is from a phase II study of Selpercatinib, a RET tyrosine kinase inhibitor with highly selective binding." (PMID 38203714, 2023). "In this case, we present a young woman with cholangiocarcinoma who was treated with the rearranged during transfection (RET)-selective tyrosine kinase inhibitor (TKI), pralsetinib, and presented to the hospital with shortness of breath." (PMID 34258110, 2021).
gastric cancer (10 papers, 2020 to 2025). A primary or metastatic malignant neoplasm involving the stomach. "Our study identifies RET mutation as a potential driver of peritoneal metastasis (PM) in gastric cancer." (PMID 41390696, 2025). "Because of the important role which RET plays in crucial cellular processes, chromosomal rearrangements, point mutations and overexpression of the RET gene can lead to the development and progression of many tumors, including gastric cancer." (PMID 34149933, 2021). "To evaluate the clinical potential of our findings, we established a gastric PM model using the MFC mouse gastric cancer cell line and treated the mice with intraperitoneal injections of pralsetinib, a clinically used RET inhibitor, every three days." (PMID 41390696, 2025). "Apatinib mainly acts on intracellular VEGFR-2 and inhibits receptor tyrosine kinases (RTK) such as c-kit and RET, mainly clinically applied in gastric cancer." (PMID 36612173, 2022). "The knowledge about the role of GDF15 and its signaling through a GFRAL/RET-dependent complex in gastric cancer is only beginning to be recognized, similar as in other human cancers." (PMID 34149933, 2021). "The existence, the functional role and clinical relevance of GDF15 and its signaling through a GFRAL/RET-dependent complex in gastric cancer (GC) and other human tumors remain to be elucidated, despite the widespread recognition of obesity as an important cancer-predisposing factor." (PMID 34149933, 2021). "Among these patients, 91 had RET fusion-positive NSCLC, 23 had RET-mutant MTC, 7 had RET fusion-positive PTC, and 1 had RET-mutant gastric cancer." (PMID 39489747, 2024). "Among the 10 target genes, the expression of MYLK, RET and SLC6A8 was down regulated in gastric cancer, while the expression of the other 7 genes was up-regulated in gastric cancer." (PMID 34249673, 2021). "Although fusions involving NTRK or RET are uncommon in gastric carcinoma, they may be amenable to treatment with an approved therapy targeting NTRK (larotrectinib, entrectinib) or RET (selpercatinib)." (PMID 39409957, 2024).
megacolon (10 papers, 2009 to 2026). "In mice, heterozygosity for two known mutant HSCR genes, RET+/− and Ednrbsl, or RET+/− and Ednrbs genes, had no intestinal aganglionosis, whereas RET+/− mice with the homozygous Ednrbs or heterozygous Ednrbs/Ednrbsl mutations showed megacolon." (PMID 22132166, 2011).
Obesity (10 papers, 2017 to 2025). Accumulation of substantial excess body fat. "Proteins we identified as potentially linked to obesity for the first time included the RET proto-oncogene (granulysin)." (PMID 29234017, 2017). "Alternatively, obesity‐associated human‐specific changes in GDF15/GFRAL/RET complex signalling could be present, reducing its efficacy." (PMID 39907315, 2025). "The present review is focused on the structure, function, and role of RET in neurodegeneration, obesity, and cancer." (PMID 32993133, 2020). "In addition, the ligand-dependent activation of RET can be important for treating various disease conditions caused by neuronal degeneration or the disturbances of functional activity of neurons, e.g., Parkinson’s disease (PD), neuropathic pain, retinitis pigmentosa (RP), and obesity." (PMID 32993133, 2020). "Despite the known risk factors for PTC including radiation exposure, iodine uptake, obesity, and the deep research on the molecular etiology of BRAF, RAS, and RET mutations, the mechanism of the incidence and development of PTC is still unknown." (PMID 36612238, 2022).
parathyroid hyperplasia (10 papers, 2006 to 2025). A hyperplasia that involves the parathyroid gland. "In adolescents, mutations in MENIN (MEN1), RET (MEN2), CDKN1B (MEN4), and CDC73 (HPT-JT) predominate, usually leading to multiglandular parathyroid hyperplasia in syndromic forms of PHPT." (PMID 40666157, 2025).
salivary gland carcinoma (10 papers, 2017 to 2025). A carcinoma that arises from the major or minor salivary glands. "Taken together, these findings support RET as a potential therapeutic target in multiple subtypes of salivary gland carcinoma." (PMID 35957881, 2022). "RET rearrangements have been detected in a variety of human cancers, including thyroid, lung, colorectal, breast, and salivary gland cancers." (PMID 33150251, 2020). "Interestingly, a high frequency of RET fusion (42.4%), including NCOA4-RET and TRIM27-RET,has been detected in salivary intraductal carcinomas, suggesting a role of RET fusion in the development of a particular type of salivary gland cancer." (PMID 33150251, 2020). "Of these, salivary gland carcinomas are genomically different from other HNCs because they have druggable genomic alterations such as HER2, RET, and NTRK." (PMID 38668785, 2024). "Additionally, fusions observed in other subtypes of salivary gland carcinoma, such as ETV6::NTRK3 and NCOA4::RET described in secretory carcinoma and intraductal carcinoma, respectively, have been reported in SDC without any histologic evidence of these other tumor types." (PMID 41357819, 2025).
endocrine neoplasia (9 papers, 2014 to 2025). "The discovery of strong genotype–phenotype correlations that govern the development of MEN2A-associated endocrine neoplasia in MEN2 cases has prompted us to utilize the identified RET mutations for the prediction of prognosis, and for the determination of surgical concept." (PMID 24449023, 2014). "We performed RET screening in 247 subjects who were referred to the Brazilian Research Consortium for Multiple Endocrine Neoplasia (BRASMEN) Center in the State of Ceará." (PMID 30624503, 2018). "The lack of a family history of MTC in this family with three carriers argues that the RET Y791F variant is not an endocrine-neoplasia-susceptibility variant." (PMID 25425582, 2015). "However, while the other three did not have a family history of endocrine neoplasia, another had three relatives positive for the same RET pathogenic variant." (PMID 40277809, 2025).